ITGB1 (integrin subunit beta 1)
Diseases named in the same sentence as ITGB1 in open-access papers (continued):
Sharing a sentence is not in itself a finding about the gene and the disease.
gastric cancer (continued). "Subsequently, we suppressed β-catenin and BCL2 expression in collagen cultured ITGB1 positive cells, and then examined the cytotoxicity of 5-FU to gastric cancer cells." (PMID 34319913, 2021). "In summary, our results demonstrate that type I collagen is capable of promoting the TIC phenotype in gastric cancer cells via the ITGB1/YBX1/SPP1/NF-κB signaling pathway." (PMID 34758833, 2021). "Further analysis of the interaction between the nodes of the PPI network revealed that 31 proteins in the characteristic genes of gastric cancer were connected to the ITGB1 protein." (PMID 34326374, 2021). "Mechanistically, we demonstrated that type I collagen was capable of promoting the activation of BCL9L/β-catenin signaling pathway through ITGB1, thereby contributing to the gastric cancer development." (PMID 34319913, 2021). "More importantly, poor overall survival was observed in gastric cancer patients with high ITGB1 expression." (PMID 34319913, 2021). "Our previous data showed that the activation of ITGB1/NF-κB signaling elicits a TIC-like phenotype in gastric cancer cells, eventually resulting in the occurrence of chemoresistance." (PMID 34758833, 2021). "More importantly, the expression of ITGB1 revealed a high correlation with the overall survival of gastric cancer patients." (PMID 34319913, 2021). "Together, these results suggest that collagen promotes the TIC phenotype and gastric cancer progression through ITGB1 signaling." (PMID 34758833, 2021). "ITGB1 positive gastric cancer cells possessed strengthened capability of colony formation and proliferative characteristics in the presence of type I collagen." (PMID 34319913, 2021). "More importantly, the TCGA database further suggested poor overall survival in gastric cancer patients with high ITGB1 expression." (PMID 34758833, 2021). "The ITGB1 node degree value was 67, and patients with gastric cancer expressing more ITGB1 had significantly lower survival rates than those with low ITGB1 expression, P = 0.022." (PMID 34326374, 2021). "To eliminate TICs and reverse chemoresistance in gastric cancer, we explored the combination of the ITGB1 inhibitor LDV and the NF-κB inhibitor JSH-23 along with a chemotherapeutic agent to suppress tumor growth." (PMID 34758833, 2021). "Intriguingly, using TCGA database analysis, elevated expression level of ITGB1 was found in gastric cancer tissues compared to normal tissues." (PMID 34319913, 2021). "In gastric cancer tissues, the average score of expression of ITGB1 was 7.8, and the average score of expression of COL1A2 was 7.0." (PMID 34326374, 2021). "In gastric cancer, upregulation of telomerase reverse transcriptase suppresses the expression of miR-29a and induces the expression of ITGB1." (PMID 29423074, 2018). "In another study, RNA sequencing demonstrated that miR-29c is downregulated in gastric cancer specimens and targets ITGB1." (PMID 29423074, 2018). "In contrast, overexpression of hTERT in gastric cancer cells promoted the expression of ITGB1 and accelerated the invasion of gastric cancer cells." (PMID 26903137, 2016). "In conclusion, we have demonstrated that hTERT enhances ITGB1 protein levels via the down-regulation of miR-29a expression, promoting the invasion and metastasis of gastric cancer cells." (PMID 26903137, 2016). "There were genomic predispositions of SNPs in the ITGA5, ITGB1, IL-10 and COX-2 genes in the children of GCA, who are considered to be a risk group of gastric cancer after H. pylori infection." (PMID 25884934, 2015). "The current study showed that the children of GCA, who are at a high risk of gastric cancer, can express with a 5-fold higher risk to be ITGA5-1160/ITGB1-1949/ITGB1 + 31804 as T/A/C carriers in ITGA5 and ITGB1 than DU." (PMID 25884934, 2015). "Consequently, the inhibitory effect of FOXO3a on integrin β1 (ITGB1) expression is reduced, resulting in elevated ITGB1 levels and increased invasiveness of gastric cancer cells." (PMID 39871386, 2025).
gastric cancer (continued). "Moreover, Maspin restrains cellular invasion and migration by preventing EMT and angiogenesis through ITGB1/FAK in gastric cancer." (PMID 40606680, 2025). "With a positive association with immunosuppressive variables and a negative correlation to immunoreactive factors, ITGB1 has also been discovered as a predictive biomarker linked to immunosuppression in gastric cancer." (PMID 38402311, 2024). "Previous studies have indicated the mechanisms of ITGB1 in gastric cancer progression." (PMID 37667169, 2023). "We analyzed ITGB1 expression in our hospital samples of the gastric cancer cohort." (PMID 35864742, 2023). "Similarly, the results of the Kaplan–Meier plotter verified that ITGB1 was a promising biomarker in gastric cancer." (PMID 37667169, 2023). "Served as fundamental component in extracellular matrix, Type I collagen could upregulate the expression of BCL9L through ITGB1, resulting in the activation β-catenin signaling pathway, thereby contributing to the gastric cancer development." (PMID 37667169, 2023). "GEPIA data were used to evaluate the prognostic value of ITGB1 in gastric cancer (GC)." (PMID 37667169, 2023). "Moreover, high expression of ITGB1 has been reported to significantly promote the invasion of gastric cancer." (PMID 36178365, 2022). "Furthermore, increased expression of ITGB1 is also involved in poor prognosis of ovarian cancer, gastric cancer, head and neck squamous cell carcinomas, and lung cancer." (PMID 36293493, 2022). "Interestingly, ITGB1 upregulation can promote the progression and invasion of gastrointestinal tumors, such as hepatocellular carcinoma and gastric cancer." (PMID 34722263, 2021). "In contrast with previous reports, we also confirmed that the ITGB1/YBX1/SPP1/NF-κB signaling axis is correlated with drug resistance development in gastric cancer, and blockade of ITGB1/NF-κB signaling led to improved anticancer effects in a subcutaneous gastric cancer mouse model." (PMID 34758833, 2021). "The similar result was confirmed at the protein level by western blotting, indicating that ITGB1 might be involved in gastric cancer progression induced by collagen." (PMID 34758833, 2021). "Taken together, these results support the notion that a combination of ITGB1/NF-κB inhibitors and chemotherapy could serve as an efficient strategy to reverse chemotherapy resistance and improve anticancer effects in gastric cancer therapy." (PMID 34758833, 2021). "Therefore, we confirmed that 3D collagen gels stimulate elevated expression of YBX1 and SPP1 through ITGB1 in gastric cancer." (PMID 34758833, 2021). "Together, those results implicated that collagen could mediate the tumor progression and drugs resistance through the ITGB1 in gastric cancer." (PMID 34319913, 2021). "Since Wnt/β-catenin served as the downstream signal of BCL9, we supposed that ITGB1 might upregulate BCL9L to mediate the activation of pro-survival β-catenin signals in gastric cancer." (PMID 34319913, 2021). "Through immunohistochemical analysis of tumor samples and adjacent tissues of gastric cancer patients, the results showed that in normal tissues adjacent to cancer, the average score of ITGB1 expression was 1.6 points, and the average score of COL1A2 expression was 2.2 points." (PMID 34326374, 2021). "As ITGB1 correlated with the overall survival and tumor progression in gastric cancer patients, we thus questioned whether ITGB1 might regulate cells proliferation to promote gastric cancer development." (PMID 34319913, 2021). "Our previous results have provided evidence that activation of β-catenin signals induced by collagen/ITGB1 could facilitate the chemotherapy resistance in gastric cancer." (PMID 34319913, 2021). "Indeed, we found that gastric cancer cells in collagen gels exhibited dramatic activation of ITGB1 signaling, and ITGB1 silencing suppressed the TIC phenotype in tumor cells." (PMID 34758833, 2021).
gastric cancer (continued). "We provided evidence that type I collagen could mediated the gastric cancer progression and chemotherapy resistance through an ITGB1 dependent manner." (PMID 34319913, 2021). "This indicates that ITGB1 might participate in gastric cancer progression through YBX1/SPP1 signaling." (PMID 34758833, 2021). "Furthermore, we used a combination of ITGB1 and NF-κB pathway inhibitors to eliminate TICs and reverse drug resistance, representing an innovative therapeutic avenue for gastric cancer therapy." (PMID 34758833, 2021). "Meanwhile, transwell and cell apoptosis analysis revealed that blockade of ITGB1 signaling resulted in cell migration inhibition and chemoresistance suppression, indicating that collagen promotes TIC properties through ITGB1 dependent signaling in gastric cancer." (PMID 34758833, 2021). "Interestingly, hTERT enhances the growth, migration and invasion of gastric cancer cells via the indirect upregulation of ITGB1, through the repression of tumor suppressor miR-29a." (PMID 28291810, 2017). "Moreover, the expression level of ITGB1 and the invasion potential of gastric cancer cells were partially decreased after the restoration of miR-29a levels by miR-29a mimics." (PMID 26903137, 2016). "We therefore hypothesized that hTERT can enhance ITGB1 expression, which occurs, at least in part, by the down regulation of miR-29a expression, to promote the invasion and metastasis of gastric cancer cells." (PMID 26903137, 2016). "To determine whether the mediation of invasive potential and the promotion of ITGB1 expression by hTERT require miR-29a, we knocked down hTERT expression in the gastric cancer cell line SGC7901 by using short hairpin construsts." (PMID 26903137, 2016). "We then examined the expression of miR-29 and ITGB1 in the tumors of patients with gastric cancer." (PMID 26903137, 2016). "We found that the up-regulation of hTERT in gastric cancer cells could inhibit the expression of miR-29a and enhance the expression of Integrin β1 (ITGB1)." (PMID 26903137, 2016). "While the roles of ITGB1 in gastric cancer were remain unknown, especially in DGC." (PMID 37007126, 2023). "Maspin was also reported to inhibit gastric cancer (GC) cell invasion and migration by blocking the cellular ITGB1/FAK signaling pathway and in turn reducing epithelial–mesenchymal transition (EMT) and angiogenesis." (PMID 36523976, 2022). "ITGB1/NF-κB targeted therapy might provide innovative inroads into gastric cancer treatment." (PMID 34758833, 2021). "However, we found the presence of type I collagen could promote ITGB1 positive gastric cancer cells colony formation and growth, thereby resulting in the tumor progression." (PMID 34319913, 2021). "Similarly, a high level of ITGB1 predicts poor survival in breast and gastric cancers." (PMID 30642292, 2019). "Further downregulation of miR-29a in GC cells by antagomiRs abrogated the effects of hTERT downregulation; this led to a partial restoration of the ITGB1 protein level, and the invasive and metastatic potentials of gastric cancer cells were partially reversed." (PMID 26903137, 2016). "In gastric cancer cells, overexpression of miR-29a could reduce the protein expression of ITGB1." (PMID 26903137, 2016). "In gastric cancer (GC), SERPINB5 upregulates ITGB1 and promotes epithelial mesenchymal transition (EMT), while MFAP2 also upregulates ITGB1." (PMID 38279122, 2024). "The dysregulation of LHPP expression leads to the upregulation of IGF1R, thereby activating the downstream ITGB1–FAK–SRC/YAP–c‐MYC signaling pathway, resulting in the development and progression of gastric cancer." (PMID 38292328, 2024). "GATA6 which located on chr18q11.2 locus (amplified in ITGB1 low subgroup), suppressed migration and metastasis by regulating the miR-520b/CREB1 axis in gastric cancer." (PMID 37007126, 2023).
gastric cancer (continued). "CD31 induces hepatocellular carcinoma epithelial–mesenchymal transition through the ITGB1-FAK-Akt signaling pathway to regulate metastasis and can also be used as a prognostic indicator for gastric cancer in the elderly population." (PMID 35741311, 2022). "By applying a threshold of 1.5-fold change (0.58 in log2) to the log2 ratio ITGB1/CDH1, we were able to discriminate two different groups of gastric carcinoma cases." (PMID 34486077, 2022). "Compared with normal tissues adjacent to cancer, the expression of ITGB1 and COL1A2 in gastric cancer tissues were significantly increased." (PMID 34326374, 2021). "This study found that ITGB1 and COL1A2 are key genes in the development of gastric cancer and can be used as prognostic markers and potential new targets for gastric cancer." (PMID 34326374, 2021). "More importantly, suppression of BCL9L by sh RNA also suppressed the up-regulation of β-catenin in collagen cultured ITGB1 positive cells, indicating that BCL9L mediated the activation of β-catenin signals in gastric cancer." (PMID 34319913, 2021). "Meanwhile, gastric cancer patients in high stage (stage II, III and IV) exhibited higher ITGB1 expression compared with patients in stage I." (PMID 34319913, 2021). "By western blot, we found that ITGB1 expression was significantly increased in U2OS-hTERT and gastric cancer cell line SGC7901, in which hTERT was overexpressed." (PMID 26903137, 2016). "The combined genotype such as ITGA5-1160/ITGB1-1949/ITGB1 + 31804 as T/A/C carriers and COX-2-1195/IL-10-592 as G-carrier/AA, or even more specifically combined with RUNX3 + 492/TFF2-308, may thus serve as a host factor to identify the risk group of gastric cancer for an early H. pylori eradication." (PMID 25884934, 2015). "In this study, we detected the expression of KAP1, TIMP1, STC2, TLN2, SRPX2, integrin beta 1 (ITGB1) and SPARC mRNAs in peripheral blood samples from pre-operative gastric cancer patients, patients with recurrence, and healthy volunteers." (PMID 23548070, 2013). "A number of research have also revealed that ITGB1 aids in the expansion and invasion of gastric cancer, non-small cell lung cancer, and pancreatic cancer." (PMID 38402311, 2024). "Integrin beta-1 (ITGB1) is related to the tumorigenesis and progression of gastric cancer." (PMID 38259849, 2023). "Although ITGB1 and LAMC1 were both tightly related to the prognosis of gastric cancer, it was suggested that LAMC1 might be involved in a more complex molecular mechanism, rather than being directly regulated by FTO." (PMID 34277426, 2021). "Our findings demonstrated that type I collagen promoted TIC-like phenotypes and chemoresistance through ITGB1/YBX1/SPP1/NF-κB pathway, which may provide novel insights into gastric cancer therapy." (PMID 34758833, 2021). "Although cd9 has been studied to regulate the malignant progress of gastric cancer, its relationship with ITGB1 has not been reported in the literature." (PMID 34326374, 2021). "Here, we sorted ITGB1+ and ITGB1- gastric cancer cells, which were seeded into 3D collagen gels or not." (PMID 34319913, 2021). "This experiment first verified the abnormal expression of differential genes in gastric cancer tissues, then constructed a PPI network, calculated its key nodes as ITGB1 and COL1A2, and finally examined its correlation with the survival rate of patients with gastric adenocarcinoma." (PMID 34326374, 2021). "To test this possibility, we sorted ITGB1 negative/positive gastric cancer cells (SGC-7901 and BGC-823) and examined the cells proliferation." (PMID 34319913, 2021). "In TIMER 2.0, 7 cancer types had higher levels of ITGB1 expression relative to neighboring normal tissues (P < 0.05): CHOL (Colon Cancer), ESCA (Esophageal Cancer), HNSC (Head and Neck Cancer), KIRC (Kidney Clear Cell Cancer), LIHC (Liver Cancer), STAD (Stomach Cancer), THCA (Thyroid Cancer)." (PMID 38402311, 2024).
gastric cancer (continued). "In vitro, our study found that 3D collagen culture promoted the capability of colony formation and growth in ITGB1 positive gastric cancer, whereas limited colony growth was observed in ITGB1 negative gastric cancer, suggesting the role of ITGB1 in type I collagen associated tumor progression." (PMID 34319913, 2021). "Additionally, using gastric cancer cell lines and available information concerning CDH1 mutation, DNA methylation, as well as microRNA expression, we observed that the ITGB1/CDH1 inverse relationship is independent of the mechanism leading to E-cadherin inactivation." (PMID 34486077, 2022).